HLA-B (major histocompatibility complex, class I, B)
Diseases named in the same sentence as HLA-B in open-access papers (continued):
Sharing a sentence is not in itself a finding about the gene and the disease.
AIDS (continued). "Control of AIDS development in HIV-1-infected human cohorts is strongly associated with the presence of HLA-B*27:05 and -B*57:01, and adaptive immune responses to the HIV-1 Gag protein are thought to play an important role in the control of viral replication." (PMID 23705941, 2013). "For instance, HLA subtypes such as HLA-B*58 and HLA-B*27 provide prolonged protection against HIV-1 infection and are associated with delayed onset of AIDS, while the converse is true of HLA-B*08." (PMID 24015196, 2013). "The strongest HLA-B aa site implicated is identical to the single aa site that mediates HLA-B*35 rapid AIDS progression reported previously." (PMID 23209447, 2012). "Subsequent HLA-class I typing and KIR genotyping determined that the activating KIR allele KIR3DS1, in combination with HLA-B Bw4-80Ile, is associated with delayed progression to AIDS." (PMID 23346087, 2012). "It has been shown that the influence of HLA-B*35 in accelerating progression to AIDS is mostly attributable to HLA-B*35-Px alleles." (PMID 22577363, 2012). "Given the strong association of HLA-B*5701 with sustained viral control and prolonged AIDS-free survival, the impact of SNPs in strong linkage with this allele warrants further investigation." (PMID 22808100, 2012). "For example, patients who possess HLA-B*27 and -B*57 alleles normally have low viral loads and progress to AIDS at a much slower rate, while those possessing HLA-B*35 progress to AIDS defining illnesses rapidly." (PMID 22666249, 2012). "The expression of KIR3DS1, an activating KIR receptor, has been shown to delay AIDS progression when its ligand, HLA-B Bw4 alleles with an isoleucine at position 80 (HLA-B Bw4-80Ile), is coexpressed in an individual." (PMID 22194686, 2011). "In a large cohort study, more than 50 per cent of white subjects possessing the HLA-B*35-Px or HLA-B*53 allele progressed to AIDS within 6 years, while it took over 11 years for this to occur in a similar percentage of subjects not possessing the alleles." (PMID 20219734, 2010). "It was noteworthy that the degree of enrichment of subjects with the HCP5-G allele with increasing AIDS-free status was similar to that observed for the HLA-B*5701 subtype." (PMID 18982067, 2008). "For example, HLA-B*57 is among the most intensively studied alleles in the HIV-AIDS field as it is among the most protective HLA class I alleles." (PMID 18982067, 2008). "Consistent with the results of the univariate analyses, with increasing AIDS-free status, there was a statistically significant step-wise increase in the proportion of subjects possessing a HLA-B*57 allele, including the B*5701 allele." (PMID 18982067, 2008). "Association of the HLA class I region, independent of known HLA class II effects, has now been detected for several AIDs, including strong association of HLA-B with type 1 diabetes and HLA-C with multiple sclerosis and Graves’ disease." (PMID 19412418, 2007). "Hypersensitivity to abacavir, a nucleoside reverse-transcriptase inhibitor commonly used for anti-AIDS treatment, has been reported to be associated with an HLA-B allele (HLA-B*5701) and a haplo-typic Hsp70-Hom variant in the HLA region." (PMID 18007983, 2007). "Indeed, most adults living with HIV expressing the protective HLA-B*57 allele progress to AIDS despite having access to the same HLA-B*57-restricted epitopes as HLA-B*57-positive individuals with EC." (PMID 34757843, 2022). "HLA-B*35 is associated with a rapid progression to AIDS and poor clinical outcomes (26, –, 31)." (PMID 34523962, 2021). "HLA-B*35Px is associated with HIV-1 disease rapid progression to AIDS." (PMID 32760139, 2020). "Natural killer (NK) cells also play a role in controlling viral replication, and genetic studies demonstrate that specific combinations of killer cell immunoglobulin-like receptor (KIR) alleles and HLA subtypes including HLA-B*57 correlate with delayed progression to AIDS." (PMID 32266164, 2020).
AIDS (continued). "Moreover, HLA-B typing indicated that the HLA-B*57 allele, which has been associated with both delayed progression to AIDS and decreased susceptibility to HIV-infection, is significantly more common than expected among HESN homozygous for rs2549782-G." (PMID 32183384, 2020). "The HLA-B*08, -B*35, -B*53, -B*55, and -B*56 alleles are associated with rapid progression to AIDS." (PMID 30147699, 2018). "HLA-B alleles have strong influences on AIDS progression outcomes and viral loads." (PMID 29989547, 2018). "The first evidence for a role of KIR3DS1 in viral infections came from genetic studies in HIV-infected individuals, indicating that an epistatic interaction between KIR3DS1 and HLA-B Bw4-80Ile delayed progression to acquired immunodeficiency syndrome." (PMID 29075265, 2017). "Indeed, a study in slow progressors to AIDS reported increased polyfunctionality of NK cells from donors carrying the KIR3DL1*h/*y allele together with its HLA-B*57 ligand compared to HLA-Bw6 homozygous donors." (PMID 29184550, 2017). "Specific HLA class I alleles like HLA-B*57 and B*27 have consistently been shown to display protective effects and are associated with viral load control and delayed progression to AIDS, while the allelic group HLAB*35Px is associated with accelerated disease progression." (PMID 29333522, 2017). "Carriage of the genetic combination encoding a high expression inhibitory Killer Immunoglobulin-like Receptor (KIR)3DL1 with its ligand, HLA-B*57 (*h/*y+B*57) is associated with slower time to AIDS and better HIV viral load control than being a Bw6 homozygote (Bw6hmz)." (PMID 24453969, 2014). "Interestingly, in our findings the shifting responses towards the mutant antigens where partly restricted by HLA-alleles associated with faster progression to AIDS (HLA-B*35:01, HLA-A*01)." (PMID 24312453, 2013). "It has also been reported that HLA-B*27, B*57 and B*51 are associated with delayed onset of AIDS." (PMID 23251376, 2012). "A larger study published in 1999 established the association of C*04 and B*35 with rapid development of AIDS-defining conditions in Caucasians, and also showed that maximum homozygosity at the HLA-B locus was more detrimental than homozygosity at either HLA-A or -C." (PMID 22571741, 2012). "It is also relevant that the same location of HLA-B amino acid position 116 has also been definitively implicated as the single aa site that drives high susceptibility of the HLA-B*35 association with very rapid AIDS progression in HIV-1 infected European Americans." (PMID 23209447, 2012). "It has, however, been suggested that the HLA-B*53 allele, which causes faster progression to AIDS, may be associated with resistance to HIV." (PMID 20219734, 2010). "Certain HLA alleles, such as HLA-B*57 and HLA-B*27, are associated with slower progression to AIDS." (PMID 20219734, 2010). "The ligand for KIR3DS1 has not been determined, although it has been shown that the KIR3DS1 activating receptor in combination with HLA-B alleles that encode molecules with isoleucine at position 80 (HLA-B Bw4-I80) results in delayed progression to AIDS after HIV-1 infection." (PMID 16805919, 2006). "It is notable that HLA-B*53 is strongly associated with accelerated progression to AIDS following HIV infection, which suggests that a potential common immunopathogenetic mechanism independent of any pathogen-derived epitope may be responsible for our findings." (PMID 33815410, 2021). "Specifically, genes encoding high 3DL1 allotypes provided greater protection from progression to AIDS when found in combination with Bw4 80I alleles (including HLA-B*57:01), whereas low 3DL1 variants enhanced protection associated with the Bw4 80T allele HLA-B*27:05." (PMID 24563253, 2014). "Combinations of alleles at the HLA-B and KIR3DL1 loci can protect against disease progression and viral load, also showing a protective effect against AIDS." (PMID 40244151, 2025).
AIDS (continued). "We analyzed the magnitude of HLA-A-restricted, HLA-B-restricted, or HLA-C-restricted T-cell responses under cART in AIDS patients." (PMID 37877716, 2023). "A rare group of HIV-infected individuals with HLA-B*35Px rapidly progress to AIDS but those with HLA-B*27 and HLA-B*57 spare disease progression." (PMID 32760139, 2020). "The US FDA, US HHS, EMA, Canada HCSC, and multiple international HIV/AIDS organizations suggest HLA-B*57:01 genetic testing is required before the first use of abacavir." (PMID 32714190, 2020). "Over the next 2–3 years, however, despite the co-expression of HLA-B*27:05 and HLA-B*57:01, progression to AIDS (absolute CD4+ T cell < 200 cells/mm3) occurred rapidly, in association with viral loads increasing to > 105 copies/ml." (PMID 29338738, 2018). "Some HLA-B locus alleles are associated with poor CTL response, high viremia, and rapid progression to AIDS in Caucasians and African-American populations infected with HIV-1 subtype-B." (PMID 28326304, 2017). "Conversely, the genotype KIR3DS1/HLA-B Bw4-80I, which stimulates NK cell activation, has been shown to promote virus containment and delay progression to AIDS." (PMID 28050553, 2016). "This clade includes human HLA-B*57:01, the HLA-B allele that has the strongest association with control of VL and delayed progression of HIV-1 infection to AIDS." (PMID 26020813, 2015). "One particular version—HLA-B*57:01—is strongly associated with having a lower viral load of HIV and progressing more slowly to full-blown acquired immunodeficiency syndrome (AIDS)." (PMID 26020235, 2015). "The genotype combinations that confers the highest degree of protection in terms of time to AIDS and VL control is 3DL1*h/*y co-carried with HLA-B*57 (*h/*y+B*57)." (PMID 24453969, 2014). "Among all human MHC class I alleles, those encoded at the HLA-B locus have the highest degree of genetic variation and the dominant influence on HIV/AIDS." (PMID 24603468, 2014). "Three PTCs carried HLA-B*3501 (OR1, OR2 and OCP), whereas the other two (KPV and MWP) carried the HLA-B*3503 allele, which is associated with a more rapid progression to AIDS." (PMID 23516360, 2013). "In humans, HLA-B*27 and HLA-B*57 expression is correlated with control of viral loads, while HLA-B*35 expression is correlated with rapid AIDS development." (PMID 22928016, 2012). "In acquired immune deficiency syndrome (AIDS), the first genetic association described was between HIV disease progression and HLA-B alleles." (PMID 23346087, 2012). "Specifically, HLA-B*57 and HLA-B*27 are associated with slower HIV-1 disease progression, whereas HLA-B*35Px associates with a stronger susceptibility to developing AIDS rapidly." (PMID 22140359, 2011). "In the analysis carried out by Carrington, individuals carrying heterozygosity for HLA-A, HLA-B, or HLA-C each showed a longer AIDS-free period compared to their homozygote locus counterparts." (PMID 20419125, 2010). "Other HLA alleles, HLA-B*35-Px and HLA-B*53, have been linked to faster HIV disease progression and AIDS-defining illness." (PMID 20219734, 2010). "Sixth, within the context of a natural history cohort of HIV-positive individuals we find that there is a gradual enrichment of protective HLA-B*57 genotypes in subjects who remain AIDS free for a prolonged duration." (PMID 18982067, 2008). "Slower HIV reproduction is thought to be one reason that HLA-B*57 and HLA-B*5801 positive people progress to AIDS more slowly than most other HIV infected persons." (PMID 18369479, 2008). "The HLA-B*27 and HLA-B*5701 MHC class I alleles have been associated with slower progression to AIDS with maintenance of CD4+ T cell counts." (PMID 18978944, 2008). "The activating allele KIR3DS1, combined with specific HLA-B alleles, slows the progression to AIDS, whereas KIR3DS1 without these alleles is associated with a faster progression." (PMID 40244151, 2025).
AIDS (continued). "Therefore, the alleles encoding the amino acid sequences in HLA directly affect the susceptibility to certain diseases, e.g., H1N1 influenza (HLA-A*11, DRB1*10, HLA-B*35), dengue infection (HLA-B*51, HLA-B*52, HLA-B*46), AIDS (HLA-B*52), etc.." (PMID 36834479, 2023). "High KIR3DL1 cell surface expression in combination with HLA-B*57 bearing a Bw4 motif with Ile at position 80 (Bw4-80I) corresponds to delayed progression to acquired immune deficiency syndrome (AIDS) in comparison to patients lacking HLA-B*57." (PMID 34358058, 2021). "For example, disabled protectivity of the HLA-B allele without 3DS1 contrasts with 3DS1-related AIDS progression in the absence of specific HLA-B alleles." (PMID 31790432, 2019). "The clade includes human HLA-B*57:01, which is associated with long-term non-progression to AIDS and encodes −21T." (PMID 30837985, 2019). "The HLA-B*27 and -B*57 alleles, both of which carry the Bw4 motif, are associated with low HIV-1 viremia and slower progression to acquired immunodeficiency syndrome (AIDS)." (PMID 30147699, 2018). "Expression of NK activating receptor KIR3DS1 in combination with HLA-B allele is associated with delayed progression to AIDS and KIR3DS1 in the absence of HLA-B allele is associated with more rapid progression to AIDS." (PMID 29447242, 2018). "Among the class I loci, HLA-B alleles are the most polymorphic and have a major influence on CD4+ T lymphocyte count, viral set point, and therefore, on the rate of progression to AIDS." (PMID 28326304, 2017). "In particular, HLA-B*27 and -B*57 alleles expressing the Bw4 epitope and isoleucine (I) at amino acid residue 80 in combination with the activating KIR II lineage allele KIR3DS1 are associated with a delayed disease progression to AIDS." (PMID 28332079, 2017). "Indeed, it has been shown that the most frequent Patr class I molecules recognize similar HIV/SIVcpz epitopes as the AIDS-protective HLA-B*27/B*57 in humans." (PMID 28332079, 2017). "This study showed that possessing KIR3DS1 and an HLA-B allele with a Bw4 motif and an isoleucine at position 80 (HLA-Bw4I80) was associated with slower progression to AIDS, when compared to patients having only one or none of these alleles." (PMID 29184550, 2017). "The impact of the MHC in response to human immunodeficiency virus (HIV) is well recognized, with class I alleles like HLA-B*35:01 leading to rapid onset of AIDS while HLA-B*57:01 and HLA-B*27:05 confer long-term non-progression." (PMID 25860507, 2015). "We find that the low expressing promiscuous HLA-B alleles are associated with rapid progression from HIV infection to AIDS, while the high expressing fastidious HLA-B alleles are found in non-progressors." (PMID 25860507, 2015). "CD8+ CTL responses directed toward the HLA-B*51:01–restricted HIV-RT128–135 epitope TAFTIPSI (TI8) are associated with long-term nonprogression to AIDS." (PMID 24600035, 2014). "Notably, HLA-B*57:01 and -B*27:05, which associate with protection in HIV/AIDS, were among the weakest LILRB2 binders." (PMID 24603468, 2014). "Combinations of alleles at the polymorphic HLA-B locus and the NK cell surface killer immunoglobulin-like receptor locus KIR3DL1/S1 have been shown to influence time to AIDS in HIV-infected individuals and risk of seroconversion in HIV exposed seronegative (HESN) subjects." (PMID 25330014, 2014). "Patients with HIV have provided the first evidence that KIR3DL1 and HLA-B compound allotypes can variably influence disease outcomes, whereby highly-inhibitory combinations of Bw4-80I and KIR3DL1-high alleles best protect against progression to AIDS." (PMID 24919192, 2014). "However, most animals do possess (multiple) allotypes with functional characteristics similar to the AIDS-controlling HLA-B*27/B*57 molecules in humans." (PMID 23705941, 2013).
AIDS (continued). "In addition, the two other studied allotypes, although divergent in their peptide-binding anchors, also appear to target the conserved areas of the HIV/SIVcpz proteome similar to the AIDS-controlling HLA-B*27 and -B*57 molecules." (PMID 23705941, 2013). "HLA-B*5701 is associated with slower disease progression and although a large percentage of B*5701 positive individuals progress slowly to AIDS, a number of patients who carry this allele progress at normal rates." (PMID 22808100, 2012). "Thus, the median time to AIDS in individuals possessing the HLA-B*35-Px or HLA-B*53 genotype is approximately half that in the rest of the population." (PMID 20219734, 2010). "Thus, compared to subjects who developed AIDS within 2 years, HIV+ subjects who were AIDS-free for more than 10 years were 12.7, 5.6 and 2.1 times more likely to possess a HLA-B*57, HLA-B*5701 and the HLA-C5′-C allele, respectively." (PMID 18982067, 2008). "Remarkably, none of the 10 subjects categorized to group 2B progressed to AIDS, and they all had a genotype that contained a HLA-B*57 and a HLA-C5′-C allele but lacked a HCP5-G allele." (PMID 18982067, 2008). "Similarly, the success of the immune response in controlling HIV infection, and therefore the speed of progression to AIDS, is primarily determined by the particular HLA-B genes expressed by each individual." (PMID 17567519, 2007). "However, the mechanism associated with the rapid progression to AIDS in individuals possessing HLA-B-*35/B*53 alleles has not been fully-studied." (PMID 32760139, 2020). "Thus, the HLA-B*57 and HLA-B*27 alleles are strongly associated with delayed HIV disease progression whereas HLA-B*35 is associated with accelerated progression to AIDS." (PMID 31393887, 2019). "Moreover, HLA-B allele is not protective if KIR3DS1 is absent, and conversely, KIR3DS1 is related to rapid development of AIDS if particular HLA-B alleles are absent." (PMID 28326304, 2017). "Similarly, HLA-B*35:03 is associated with a fast progression to AIDS, while HLA-B*35:01 is not; these two HLA molecules differ at position 116 only." (PMID 26040913, 2015). "HLA-B*52 has been associated with resistance to HIV-1-infection, with early control after infection and with non-progression to AIDS." (PMID 36851781, 2023). "The association of the HCP5 polymorphism at rs2395029-G with HLA-B*57:01 and HIV nonprogression to AIDS was confirmed in follow-up studies." (PMID 31137555, 2019). "EC17, VC14, and EC42 did not carry an HLA-B allele or exhibit a CCR5 genetic profile associated with the control of viral replication and/or non-progression to AIDS." (PMID 30201008, 2018). "The 17-fold reduction in viral set point in HLA-B*58:02–positive vaccinees observed here equates to a >5-year AIDS-free period without ART and a >2-fold reduction in onward transmission risk." (PMID 26951820, 2016). "For human HIV-1 infections, tyrosine 116 in HLA-B correlates with reduced VL and slower progression to AIDS, whereas histidine 116 has no protective effect." (PMID 26020813, 2015). "Nonetheless, the HLA-A locus is often over-shadowed by HLA-B and HLA-C in studies of HIV/AIDS." (PMID 24969460, 2014). "The other subject initially presented the characteristic phenotype of an HLA-B*27:05/57:01-positive HIV-infected subject, with a low viral load (65 copies/ml) and high absolute CD4+ T cell count (950 cells/mm3), but within 2.7 years had progressed rapidly to AIDS (CD4+ T cell count < 200 cells/mm3)." (PMID 29338738, 2018). "We found that psoriasis patients are highly enriched for HLA-B*57:01 (12.5% in cases vs 3.9% in controls, p = 5.50×10−42, OR = 3.61), which in multiple studies has been shown to be the most significant predictor of both HIV-1 control and delayed progression time to AIDS." (PMID 22577363, 2012).